MYC (MYC proto-oncogene, bHLH transcription factor)
Diseases named in the same sentence as MYC in open-access papers (continued):
Sharing a sentence is not in itself a finding about the gene and the disease.
prostate carcinoma (continued). "In PC-3 prostate cancer cells, MYC expression was shown to be more sensitive to PPRHs, resulting in a more pronounced downregulation compared to KRAS, whereas the reverse was true in KRAS-mutant and -dependent AsPc-1 pancreatic cancer cells." (PMID 39457457, 2024). "We observed a significant reduction in BCL-2 and CDK4 expression, along with an increase in Bax and PTEN, in prostate cancer cell lines upon MYC suppression." (PMID 38756697, 2024). "Cancer-associated fibroblast infiltration has been associated with disease progression in prostate cancer, whilst high MYC TF activity induces low AR TF activity to drive disease progression and castration resistance in prostate cancer." (PMID 39574035, 2024). "METTL3 is upregulated in prostate cancer (PCa) tissues and promotes MYC expression through m6A modification, which promotes PCa cell growth and progression." (PMID 39289775, 2024). "In conclusion, we discovered that miR-377 regulates MYC mRNA in prostate cancer cell lines by targeting its 3′-UTR." (PMID 38756697, 2024). "The authors showed that mitochondrial one-carbon metabolism is differentially regulated in prostate cancer compared to normal prostate, with mTORC1 signaling supporting its upregulation in normal tissues and MYC in cancerous tissues." (PMID 40604332, 2024). "The MYC gene is a regulatory and proto-oncogenic gene that is overexpressed in the majority of prostate cancers (PCa)." (PMID 38756697, 2024). "c-MYC-positive tumors were also significantly enriched for KLF6-SV1 in human prostate cancer specimens." (PMID 38352401, 2024). "Alterations of chromosome 8, particularly amplification at 8q24 involving the MYC oncogene, have emerged as one of the most common chromosomal abnormalities in the development of prostate cancer." (PMID 38756697, 2024). "In this particular study, we have made the discovery that miR-377 exerts substantial inhibitory effects on proliferation, the cell cycle, and migration, while also inducing apoptosis in prostate cancer cell lines by specifically targeting the oncogene MYC." (PMID 38756697, 2024). "Gene set enrichment analysis revealed an association between DENND2D expression and the negative regulation of MYC target genes, including MAD2L1, ERH, and CLNS1A, which are overexpressed in prostate cancer and associated with poor survival." (PMID 39857609, 2024). "Transcriptomic and epigenomic approaches revealed that CDKI-73 suppressed signaling pathways regulated by AR, MYC, and BRD4, key drivers of dysregulated transcription in prostate cancer, and reprogrammed cancer-associated super-enhancers." (PMID 39117800, 2024). "The pSTAT4-CBP interaction serves as a critical enhancer of c-MYC transcriptional activity in prostate cancer cells." (PMID 38429845, 2024). "BET inhibitors are emerging as a potential treatment for advanced prostate cancers due to their potential impact on both MYC expression and the AR." (PMID 38379333, 2024). "MYC as a proto-oncogene, is frequently overexpressed in prostate cancer, including the most advanced and metastatic castrate-resistant cases." (PMID 38756697, 2024). "The lncRNA PCAT1 exhibits an oncogenic role in prostate cancer by post-transcriptionally inducing MYC expression and safeguarding MYC levels from miR-34a-induced repression." (PMID 39334294, 2024). "In prostate cancer, NME2 acts as an upstream regulator of MYC, and their increased activity is associated with a risk of resistance to enzalutamide, a treatment in prostate cancer." (PMID 39063217, 2024). "Taken together, these findings suggest an essential role of MYC in mtDNA replication and mitochondrial function in both Drosophila normal ovarian tissues and prostate cancer development and progression." (PMID 37971875, 2023).
prostate carcinoma (continued). "In a recent study, we identified prostate cancer rSNP, rs11986220, as a novel eQTL for the oncogenic gene MYC in a subset of samples with a high level of methylation at a CpG site located approximately 10 kilobase pairs (kbp) upstream of the MYC promoter." (PMID 38066556, 2023). "While our initial observations examined the behavior of proto-oncogene MYC across various stages of prostate cancer, we sought to examine the behavior of MYC in other cancer types, including melanoma, lung, ovarian, pancreatic, and breast." (PMID 37059746, 2023). "However, reports that decreased HECTD4 in prostate cancer leads to increased AR and MYC proteins and that increased AR/MYC is oncogenic in OSCC suggest that loss‐of‐function mutations in HECTD4 are oncogenic and may be a cause of carcinogenesis in elderly nonsmokers." (PMID 37272305, 2023). "We focus on the regulation of glutamine metabolism in prostate cancer through key pathways involving the androgen receptor pathway, MYC, and the PTEN/PI3K/mTOR pathway." (PMID 36959101, 2023). "We thus expected that AR and MYC would have convergent signaling in prostate cancer and mCRPC, but to lesser degrees in normal prostate tissue." (PMID 37059746, 2023). "In this study, we find that MYC rewires prostate cancer chromatin architecture by interacting with CTCF protein." (PMID 36997534, 2023). "In prostate cancer (PrC), the 8q24 locus contains three independent regulatory regions upstream of MYC that physically loop and interact with its promoter in a tissue-specific way." (PMID 37443779, 2023). "In prostate cancer, the redistribution of coactivators in the common super-enhancer region is dependent on the ratio of AR to MYC levels." (PMID 37443779, 2023). "HnRNPs H1 and H2 are highly similar in peptide sequence but differ in their relative expression, with H1 more highly expressed in most cell types including HEK293 cells and a MYC-dependent prostate cancer model." (PMID 37399401, 2023). "We found that HRAS exon 5 is one of a group of MYC-regulated exons that are also regulated by hnRNPs H and F, which are essential for the growth of prostate cancer cells." (PMID 37399401, 2023). "Previous literature has indicated that AR and MYC become co-regulators in prostate cancer, but only as a function of disease progression." (PMID 37059746, 2023). "In-vitro and in-vivo studies have shown that SARMs repressed MYC oncoprotein expression and inhibited the growth of castration-sensitive and castration-resistant prostate cancer." (PMID 36891053, 2023). "Another inhibitor, CCS1477, inhibits prostate cancer cell proliferation and reduces the expression of AR and c-MYC regulatory genes, making it a promising novel prostate cancer treatment." (PMID 36979352, 2023). "MYC is also a key driver of prostate cancer, and its overexpression starts early in the disease process in HGPIN, continues in primary carcinomas, and is also highly expressed in mCRPC." (PMID 37971875, 2023). "Further, they have shown that cis-NATs in the 3′ distal region are involved in tight regulation of c-MYC gene in the prostate cancer cells." (PMID 37926284, 2023). "It is a coactivator both of MYC and AR and contributes to the reprogramming of the androgen network and central metabolism in prostate cancer cells." (PMID 37443779, 2023). "Similar to AR in prostate cancer, MYC is predominantly co-amplified with the adjacent regulatory region and/or the regulatory region is amplified alone." (PMID 37443779, 2023). "To examine the potential regulation of these genes in prostate cancer by MYC, we interrogated mRNA levels of these genes after siRNA knockdown of MYC in 3 prostate cancer cell lines." (PMID 37971875, 2023).
prostate carcinoma (continued). "FABP5 amplification and surge in expression are strongly correlated to that of the MYC oncogene, a known driver of advanced PTEN-deficient prostate cancer." (PMID 38201488, 2023). "In human prostate cancer cell lines, we have shown that forced overexpression of MYC results in increased mtDNA." (PMID 37971875, 2023). "It has been shown that glutamine deficiency or inhibition of key regulators of glutamine metabolism, such as GLS and the transcription factor MYC, leads to prostate cancer radiosensitization." (PMID 36771124, 2023). "To evaluate the effects of splicing factors hnRNP H and F on the growth of MYC-transformed cells, we knocked down their expression in two prostate cancer cell lines." (PMID 37399401, 2023). "Here, we show that MYC reshapes the chromatin architecture of prostate cancer (PCa) cells through interacting with CTCF protein." (PMID 36997534, 2023). "Mechanistically, MYC inhibition in prostate cancer cells decreases mtDNA replication and expression of several mtDNA replication genes, and MYC activation in the mouse prostate leads to increased mtDNA levels in the neoplastic prostate cells." (PMID 37971875, 2023). "Here, we report that large-scale bioinformatic analyses of splicing and MYC expression confirm the correlation of HRAS exon 5 repression with the MYC signature score in prostate cancer and across many tumor types." (PMID 37399401, 2023). "For example, ectopic expression of MYC in prostate cancer leads to an increase in the expression of ACLY, ACC1, and FASN, resulting in promoted lipid accumulation." (PMID 37151387, 2023). "In human prostate cancer, MYC drove glucose metabolism via the suppression of TXNIP (a potent negative regulator of glucose uptake), which was predominantly dependent on the glutaminase-MondoA axis." (PMID 37626036, 2023). "For example, prostate cancer cells often have loss of phosphatase and tensin homolog (PTEN) that is accompanied by IRE1-driven MYC hyperactivation (in fatal-metastatic cases)." (PMID 37721642, 2023). "MYC also plays a role in regulating cancer cell motility and metastasis and is a critical oncogenic driver of prostate cancer." (PMID 37663929, 2023). "Collectively, our results reveal mechanisms for MYC-dependent regulation of splicing and point to possible therapeutic targets in prostate cancers." (PMID 37399401, 2023). "MYC is a well characterized oncogenic transcription factor in prostate cancer, and CTCF is the main architectural protein of three-dimensional genome organization." (PMID 36997534, 2023). "The cell line used in this allograft model was derived from a prostate cancer that developed in Hi-MYC mice that express the c-MYC oncogene in the prostate under the control of an androgen-regulated promoter (ARR2/probasin-Myc)." (PMID 36551505, 2022). "AR activation has previously been shown to downregulate MYC in normal prostate epithelial cells and models of prostate cancer." (PMID 36194476, 2022). "Regulates the expression of oncogenic transcription factor MYC; regulates prostate cancer cell proliferation; drives ETM transition in CRPC." (PMID 35547880, 2022). "Here we model MYC-driven prostate cancer initiation in vivo and define the transcriptional rewiring occurring in luminal cells at a single-cell level." (PMID 35562350, 2022). "In prostate cancer, Foxp3 repress the transcription of c-MYC leading to inhibition of cell cycle progression and apoptosis." (PMID 35326661, 2022). "The inherited predisposition for prostate cancer implicates prostate cell and tissue repair (DNA double-strand break and mismatch repair genes) and regeneration (HOXB13 and putative MYC enhancer) in disease pathogenesis." (PMID 35104804, 2022). "Dysregulation of alternative splicing in prostate cancer is linked to transcriptional programs activated by AR, ERG, FOXA1, and MYC." (PMID 36170835, 2022).
prostate carcinoma (continued). "In summary, our findings indicate that the MYC targeting gene Mad2L1 is potentially related to the dormancy mechanism of prostate cancer." (PMID 35305591, 2022). "Since c-MYC amplification or overexpression is frequently observed in human prostate cancers, this model is relevant to human prostate cancers." (PMID 36551505, 2022). "PCAT1 promotes prostate cancer proliferation through c-MYC via sponging miR-3667-3p and FSCN1 via sponging miR-145-5p." (PMID 35075375, 2022). "These sites were also characterized by increased H3K27ac mark (P = 3.54e-268), in agreement with the MYC-driven murine prostate cancer model." (PMID 35562350, 2022). "In cells, the PPRHs demonstrated regulation of MYC promoter activity and broad anti-cancer activity at 100 nM in breast, brain, colorectal, and prostate cancer cells." (PMID 36613820, 2022). "Analyses of clinical specimens reveal that concurrent low AR and high MYC transcriptional programs accelerate prostate cancer progression toward a metastatic, castration-resistant disease." (PMID 35562350, 2022). "In a conditional prostate cancer mouse model in which MYC is expressed under the probasin promoter (PB-MYC), the tumors were highly representative of human prostate cancers, expressed high levels of IHH, and smooth muscle cells were depleted." (PMID 36010600, 2022). "Patient-derived prostate cancer xenografts grown as organoids have increased uptake of ArA in models with increased MYC activity and PLA2G4F expression." (PMID 36181613, 2022). "These are well established oncogenic pathways in prostate cancer, driven by transcription factors AR, MYC and E2F1/2." (PMID 35406480, 2022). "Together, these data show that SWI/SNF ATPase inactivation specifically leads to genome-wide collapse of the AR, FOXA1, ERG and MYC-activated core enhancer circuitry in prostate cancer cells." (PMID 34937944, 2022). "In colorectal cancer (CRC) and prostate cancer, the MYC enhancer is located 335 kb upstream of MYC5." (PMID 35039581, 2022). "MYC amplification is also more frequent in metastatic African American (AA) prostate cancer patients." (PMID 35912174, 2022). "Hierarchical clustering was also successfully applied to the output of KODAMA to identify metabolic phenotypes in the plasma of patients with prostate cancer and visualize metabolic data for MYC- and AKT-driven prostate cancer." (PMID 36733493, 2022). "In prostate cancer, elevated MYC drives tumorigenesis, and MYC gene activation has been shown to correlate with cancer progression and poor survival." (PMID 35935969, 2022). "In AA prostate cancer cells examined here, differential expression of MYC and TOPK was observed in tumor-derived cultures as compared with cells derived from normal tissues in the prostate." (PMID 36970725, 2022). "MYC is commonly amplified in primary prostate cancer and is overexpressed in 37% of metastatic disease." (PMID 35562350, 2022). "Altogether, these data suggest that SPA inhibits growth of prostate cancer with high AR abundance in part through downregulation of MYC." (PMID 36194476, 2022). "Similar results have been shown for the CUDC-907-mediated inhibition of cancer cell growth by inhibiting MYC levels in pancreatic adenocarcinoma, acute myeloid leukemia, and prostate cancer." (PMID 35205815, 2022). "Our results suggest that SPA/BAT can significantly downregulate MYC expression, and this occurs only in prostate cancer with high AR activity." (PMID 36194476, 2022). "Using the androgen responsive LNCaP prostate cancer cell line, Barfeld and colleagues have previously reported that MYC overexpression antagonizes the transcriptional activity of the AR15." (PMID 35562350, 2022). "Although AR and MYC are both central to prostate cancer etiology, our current understanding of the interplay between these two transcription factors is scarce." (PMID 35562350, 2022).
prostate carcinoma (continued). "Using an institutional cohort of 177 laser capture microdissected (LCM) foci of primary prostate cancer (PCa), we examined the range of global gene expression that tracked with MYC transcript abundance." (PMID 36181613, 2022). "The model of lineage plasticity described in SCLC, with SCLC-A transforming to SCLC-N mediated by MYC activation, has similarities to the transformation of prostate cancer and pancreatic cancer." (PMID 36090051, 2022). "This is in accordance with prior reports that demonstrate the ability of SPA to downregulate MYC in prostate cancer cell lines, but is the first evidence that this phenomenon occurs in patients." (PMID 36194476, 2022). "MYC is a family of transcription factors and proto-oncogenes, which plays a key role in prostate cancer initiation, early progression, and metastasis." (PMID 35912174, 2022). "Considering that prostate cancer cells that develop resistance to AR-targeted therapy usually maintain AR expression, the interplay between MYC and AR is likely to remain critical as the disease progress to the CRPC stage." (PMID 35562350, 2022). "In terms of mechanisms, one study revealed that METTL3 can elevate the expression of MYC mRNA and protein levels by increasing the m6A level of the MYC transcript, which leads to carcinogenesis of prostate cancer." (PMID 36008936, 2022). "MYC expression was also found to be up-regulated in prostate cancer cells by elevated levels of ceRNA MYU which binds miR-184." (PMID 34440124, 2021). "The MYC transcription factor family is important for many cancers in addition to prostate cancer, which is why their interactomes have been of relevance to many." (PMID 34638309, 2021). "PCAT1, a lncRNA that maps approximately 710 kb upstream of the MYC gene, is responsible for the post-transcriptional regulation of MYC in prostate cancer." (PMID 33435206, 2021). "We called 125,569 peaks and identified differentially accessible peaks around the promoter regions of several key genes in prostate cancer such as MYC and KLK3." (PMID 34911933, 2021). "Androgen receptor in prostate cancer (PCa) transcriptionally represses multiple genes including MYC." (PMID 34911936, 2021). "Androgen receptor (AR) in prostate cancer (PCa) can drive transcriptional repression of multiple genes including MYC, and supraphysiological androgen is effective in some patients." (PMID 34911936, 2021). "MYC is one of the most highly expressed genes in prostate cancer, and has been shown to positively regulate the AR and its splice variants." (PMID 35008216, 2021). "High-level ribosomal proteins amplifications and MYC amplifications were observed in castration-resistant prostate cancer samples of the publicly available Stand Up to Cancer data set." (PMID 33705753, 2021). "Recently, it has also been found that the expression of miR-449a in prostate cancer cells increases in response to ionizing radiation at a dose of 4–8 Gy and, by suppressing the expression of the MYC gene, increases the sensitivity of these cells to radiation." (PMID 34440124, 2021). "Our study and other findings demonstrated that prostate cancer cells exhibit different sensitivities towards inhibition of MYC and Gln deprivation." (PMID 34335968, 2021). "An analysis was applied to compare the correlation between predicted 6-gene signature and conventional clinical factors of prostate cancer, Results showed that MYC expression was correlated with patients’ age (P = 0.009)." (PMID 33402116, 2021). "Another lncRNA has been shown to be involved in the regulation of MYC gene expression in prostate cancer cells." (PMID 34440124, 2021). "Chromosomal region 8q24, the site harboring the gene coding for transcription factor c-MYC, is often amplified in prostate cancer." (PMID 34638309, 2021). "Previous research has established a link between UPR and c-MYC, and it is known that the IRE1α–XBP1s pathway promotes prostate cancer development by activating c-MYC signaling." (PMID 34663798, 2021).